BUB1 (BUB1 mitotic checkpoint serine/threonine kinase)
Diseases named in the same sentence as BUB1 in open-access papers (continued):
Sharing a sentence is not in itself a finding about the gene and the disease.
cancer (continued). "Consistently, while overexpression of some SAC genes such as MAD2 and BUB1 has been shown to induce CIN and cancer onset, overexpression of BUBR1 has protective effects on spontaneous tumor development and accumulation of aneuploidy." (PMID 26015801, 2015). "Indeed, although it has also been demonstrated that mice carrying conditional Bub1 mutation develop severe defects ranging from early lethality to tumorigenesis, even SAC gene overexpression has been reported to impair the spindle assembly checkpoint playing a critical role in cancer progression." (PMID 26009897, 2015). "Changes in expression profiles of BUB1 and BUBR1 are often encountered in cancer cells and result in the impairment of mitotic checkpoint function." (PMID 20888775, 2011). "Many of these genes function in inflammation (CXCR3, EOMES, IL18R1, GZMM, IL2rb), metastases (CXCR3, BUB1), poor outcome cancers (EOMES, BUB1), or stem cells (EOMES, BUB1)." (PMID 22053823, 2011). "Amongst these are regulators of mitosis e.g. BUB1, CDC20, and PBK, which are known to play important roles in the ontology of various types of cancers." (PMID 18847459, 2008). "Additionally, BUB1 promotes GC cell proliferation and metastasis through METTL3-mediated m6A methylation, highlighting its critical role in both mitosis and cancer progression." (PMID 40949882, 2025). "Despite exhibiting a relatively lower CRISPR viability score in H28 cells, BUB1 depletion imposed a pronounced and selective growth disadvantage in cancer cells compared to nonmalignant controls." (PMID 40180891, 2025). "BUB1 and BUB1B mutations have been associated with an increased risk of colon cancer but have not been linked with other cancers." (PMID 39048649, 2024). "Dysregulated expression of BUB1 and BUB1B led to cancer cell proliferation." (PMID 38375472, 2024). "Indeed, most cancers and in vitro analyses showed sensitivity to EGFR/VEGFR targeting drugs, coherent with BUB1’s role in regulating membrane signalling." (PMID 38396175, 2024). "Notably, as co-expressed genes, TOP2A, BUB1 and CENPE also interacted with the CENPF protein, the high expression of which predicted poor prognosis in cancers." (PMID 37108172, 2023). "The first were tightly regulated, through MELK, BRCA2, KIF14, BUB1, and TOP2A, by five TFs (NFE2L3, RUNX1, RUNX2, BHLHE40, and the aging cancer-specific SOX11), two LncRNAs (ST7OT1 and CDKN2BAS), and four miRNAs (miR-21-5p, miR-363-3p, miR-873-5p, and miR-138-1-3p)." (PMID 37191407, 2023). "A negative correlation between bub1 expression and immune infiltration of the cancer microenvironment was found." (PMID 36237324, 2022). "3D cultured cells were also shown to have lower levels of genes related to cell proliferation or mitosis (CCNA2, MKI67, and BUB1) and differentiation (ESR1) relative 2D cultured, consistent with higher levels of a cell cycle inhibitor (CDKN1) and cancer stemness–related markers (CD44 and MALAT1)." (PMID 34869246, 2021). "We verified whether the BUB1 transcript with the extended 3’UTR was naturally expressed in normal and cancer cells." (PMID 29560129, 2018). "BUB1 is a molecular component of the spindle checkpoint and required for proper checkpoint signalling and deletions of BUB1 or BUBR1 were detected in several cancers." (PMID 29618387, 2018). "For example, in the seven cancer types (BLCA, ESCA, HNSC, KIRC, LIHC, STAD and UCEC) with both grade phenotype information and normal control samples, expression of AURKB, BUB1, FOXM1, HMMR, MYBL2, and PLK1 follows the pattern in five cancer types (BLCA, HNSC, KIRC, LIHC, and UCEC)." (PMID 28427185, 2017). "In agreement with the observations in cancer cells, we find that protein level of Bub3 is markedly reduced upon knockdown of Zfp207, rather than that of Bub1, BubR1 and Mad2." (PMID 27177335, 2016).
cancer (continued). "In addition, a subset of these genes have been identified as markers for poor outcomes in lymphoid and other cancers (CXCR3, EOMES, BUB1)." (PMID 22053823, 2011). "Cellular and molecular studies demonstrate that genetic depletion or pharmacological inhibition of BUB1 profoundly impairs MPM cell survival and growth while inducing G2/M cell cycle arrest, cellular senescence, and apoptosis, and attenuating functional hallmarks of aggressive cancer cells." (PMID 40180891, 2025). "A gene set enrichment analysis using the proteins that interact with BUB1 showed that MRAN surveillance pathway, microRNAs in cancer, osteoclast differentiation, pathways in cancer, splicesome, and transcriptional misregulation in cancer could be the pathways involved in BUB1 overexpression." (PMID 40723917, 2025). "In addition, several studies have demonstrated that CDK1, through phosphorylation of BUB1, EZH2 and PPP1CA, alters cell cycle regulation, chromosome segregation, epigenetic control, and DNA replication, leading to cell dysfunction and diseases such as cancer." (PMID 38831458, 2024). "Therefore, the molecular function of BUB1 and BUB1B genes in HD cancers should be further examined." (PMID 35757968, 2022). "Consistent with the hypothesis that CIN is sufficient to initiate cancer, heterozygous offspring of Mad1, Mad2 and CENP-E knock-out mice, as well as offspring of a Bub1 hypomorphic mouse strain showed increased incidence of spontaneous tumors mainly in the lung and the hematopoietic system." (PMID 26015801, 2015). "Therefore, the common DNA damage phenotypes of the replisome mutants described here could explain the SL relationship with cancer CIN genes involved in DNA repair (MRE11/SGS1) and the cell cycle (BUB1)." (PMID 23390603, 2013). "However, the expression and roles of BUB1 and BUB1B in pan-cancer and EC is unknown." (PMID 39048649, 2024).
tumor (134 papers, 2007 to 2026). "BUB1B, a member of the spindle assembly checkpoint family known as BUB1 mitotic checkpoint serine/threonine kinase B, has been associated with the promotion of tumor progression." (PMID 40076684, 2025). "BUB1 inhibition causes significant decrease in tumor volume when combined with radiation in SUM159 mammary fat pad tumor xenograft models and demonstrates significant reduction in tumor cell proliferation as evaluated by Ki67 immunostaining of tumor sections." (PMID 38863037, 2024). "BUB1 was associated with abundance of a variety of tumor-infiltrating lymphocytes (TILs) and mostly showed a negative correlation." (PMID 39048649, 2024). "It has been shown that elevated BUB1 expression associated with the abundance of tumor-infiltrating mast cells in ACC patients is significantly related with poor prognosis." (PMID 38053725, 2023). "Although BUB1 seems to be a tumor suppressor, enhanced BUB1 expression causes chromosome instability and further induced oncogenesis." (PMID 33477943, 2021). "BUB1 was identified as a prospective prognostic marker whose upregulation is associated with poor clinical outcomes in diverse tumor types." (PMID 34884561, 2021). "In our cohort of 218 patients with GC we can demonstrate that frequent BUB1 expression in tumor nuclei is associated with a good prognosis in patients with GC, and that BUB1 in only a small fraction of tumor cells is associated with a poor prognosis." (PMID 29100315, 2017). "Tumors with low frequency of BUB1 expression were associated with larger tumor size (pT) (p < 0.001), higher incidence of lymph node metastases (pN) (p = 0.027), distant metastases (pM) (p = 0.006) and higher UICC stage (p < 0.001)." (PMID 29100315, 2017). "Overexpression of BUB1 and other family members has been found to be associated with tumor cell proliferation." (PMID 26287798, 2015). "Although mounting evidence suggests that high MAD2L1 or BUB1 are associated with tumor progression, study findings have been inconsistent." (PMID 26287798, 2015). "In another study the same group added Bub1-induced aneuploidy to a background of heterozygosity for a panel of tumor suppressors and identified induced loss of heterozygosity of these tumor suppressors as one mechanism of action for Bub1 oncogenesis." (PMID 21403899, 2011). "Transactivation of BUB1 by MYB may promote tumour development, since overexpression of BUB1 cause hyper‐activation of Aurora B activity, aneuploidy, and spontaneous and MYC‐induced transformation in a transgenic mouse model." (PMID 38112379, 2024). "In addition, the increased expression level of BUB1 was further shown to be closely associated with tumor cell proliferation." (PMID 36863706, 2023). "Thus, our study suggested that overexpression of BUB1 protein contributed to poor survival of OS patients and that inhibition of BUB1 resulted in considerable anti‐tumour activity associated with proliferation, migration, invasion and apoptosis of OS." (PMID 34337852, 2021). "Interestingly, overexpression of STAT3-Flag in BCa cells not only restored their proliferation but also reversed the impairment of tumor sphere formation caused by BUB1 knockdown." (PMID 34852826, 2021). "It is reasonable to assume that an attack to tubulins by drugs in tumors where BUB1 appears mutated may drift the tumor population towards extinction by exceeding the limits of mutation tolerance." (PMID 20015360, 2009). "BUB1 inhibition reduces tumor growth and cell proliferation through PI3K/AKT signaling pathway inhibition." (PMID 40723917, 2025). "Radiosensitization in TNBC tumor xenografts with tumor growth delay and decreased overall survival was observed in BUB1 (cell cycle Ser/Thr kinase) ablation of TNBC cells suggesting that BUB1 is a possible target and responsible for radiosensitization." (PMID 40141437, 2025).
tumor (continued). "Specifically, PIWIL4, SATB1, GSE1, NCOR1, SAP30L, ATM, and BMI1 were significantly downregulated in tumor tissues relative to normal controls, while BUB1, CHEK1, MASTL, DNAJC2, UBE2D1, and SSRP1 showed pronounced upregulation." (PMID 41208974, 2025). "Crucially, the demonstration that BUB1 is essential for aggressive MPM tumor cell fates, combined with its elevated expression predicting poor patient prognosis, strengthen the rationale for its therapeutic exploitation." (PMID 40180891, 2025). "These novel findings suggest that MPM tumor-promoting activities of BUB1 depend, at least in part, on its kinase function and provide support for the druggability of this kinase in MPM." (PMID 40180891, 2025). "Although BUB1 overexpression is a common phenomenon related to tumour proliferation in various solid tumours, studies of BUB1 in tumour CIN have been limited." (PMID 38498903, 2024). "Only patients with high expression of ESR1 and BUB1 in tumor tissue showed a worse prognosis in terms of overall survival (OS) compared to those with low expression." (PMID 38831458, 2024). "Genes such as BUB1, TPX2, and ESPL1 demonstrated significant associations with patient survival outcomes and tumor progression, suggesting their potential utility as prognostic biomarkers for risk stratification and treatment selection." (PMID 39596419, 2024). "Specifically, we found statistically significant associations between the expression of BUB1 and TNM classifiers (i.e. tumour size, lymph node, and metastasis status), grading and staging in several tumours." (PMID 38396175, 2024). "Although the body weight of each group was similar, the tumour formation was significantly reduced in animals implanted with BUB1 knockdown cell‐derived xenografts (6/8)." (PMID 38498903, 2024). "The expression of BUB1 showed a strong performance in distinguishing normal vs tumour tissues in the majority of sites, as determined by AUC values defining sensitivity and specificity of the marker." (PMID 38396175, 2024). "Consistently, the average tumour volume in the BUB1‐KD group (192.7 ± 78.0 mm3) was also nearly 65% smaller than that in the BUB1‐WT group (550.8 ± 204.3 mm3)." (PMID 38498903, 2024). "BUB1 knockdown remarkably repressed tumour growth and tumour formation of nude mice with ATC xenografts and suppressed tumour metastasis in a zebrafish xenograft model." (PMID 38498903, 2024). "Our BUB1 immunostaining TMA data support earlier findings wherein nuclear BUB1 staining was found to strongly correlate with stage, pathological tumor factors, lymph node metastasis, distant metastasis, histological grade, and proliferation." (PMID 38863037, 2024). "The changes in the NF2/MOB1-YAP signaling pathway in tumor cells after BUB1 knockdown and GEM treatment were examined using Western blot." (PMID 38672622, 2024). "High mRNA expression of CDK1, PCNA, EZH2, BUB1, and CXCR4 in tumor was significantly associated with lower RFS." (PMID 38831458, 2024). "Our TMA analysis found strong correlation between BUB1 protein expression and tumor grade and identified high BUB1 expression in TNBC samples." (PMID 38863037, 2024). "Overexpression of BUB1 was showed to promote tumor cell proliferation, migration, invasion, and reduce apoptosis." (PMID 38440734, 2024). "Compared to the PANC-1 group, treatment with GEM or BUB1 knockdown significantly reduced tumor volume and weight in mice." (PMID 38672622, 2024). "H&E staining indicated that the BUB1‐KD group of tumour tissues contained fewer tumour cells than tumours in the BUB‐WT group mice." (PMID 38498903, 2024). "Excitingly, the mean tumour weight was obviously lower in the BUB1‐KD group (248.6 ± 99.8 mg) than that in the BUB1‐WT group (638.3 ± 290.1 mg) (p < 0.01)." (PMID 38498903, 2024). "Immunofluorescence results showed that compared to the PANC-1 group, both GEM treatment and BUB1 knockdown led to a significant decrease in Ki67 staining in tumor tissues." (PMID 38672622, 2024).
tumor (continued). "We observed significant correlation between BUB1 protein expression (staining intensity) and tumor grades and stages." (PMID 38863037, 2024). "Overall, these results indicated that BUB1 is overexpressed in the majority of TCGA tumours and that its expression is elevated in molecular subtypes associated with clinical aggressiveness." (PMID 38396175, 2024). "BUB1 ablation also led to radiosensitization in TNBC tumor xenografts with significantly increased tumor growth delay and overall survival." (PMID 38863037, 2024). "As a member of the mitotic checkpoint family, BUB1 was upregulated in GC and correlated with the tumor histological subtype." (PMID 36863706, 2023). "Next, we performed qRT-PCR and western blot to further validate the higher mRNA and protein levels of BUB1 in PCa cell lines and clinical tumor tissues." (PMID 35659274, 2022). "CIN (chromosomal instability) is a common feature of many malignant cells and both increased and decreased SAC gene expression (Mad2, BUB1) induces aneuploidy and favors tumor development." (PMID 34882895, 2022). "Overexpression of BUB1 in tumor tissues is also considered to be a biomarker for poor prognosis in tumor patients." (PMID 35859798, 2022). "BUB1 and BUB1B suppress the immune response by increasing the expression of immune checkpoint molecules, causing tumor cells to form immune escape." (PMID 35493295, 2022). "In particular, the HR for BUB1 expression was higher than that for tumor grade in the training cohort (6.076 vs. 5.508; p < 0.05)." (PMID 34884561, 2021). "Bub1 overexpression in mice resulted in aneuploidy and tumor formation likely mediated through Aurora B hyperactivation." (PMID 33717411, 2021). "Because tumor stage and grade are the most common predictors of tumor prognosis, these results suggest that the upregulation of BUB1 is a prognostic indicator of NMIBC." (PMID 34884561, 2021). "We also found that the expression of BUB1 in the tumor epithelium progressively increased in BCa tissue compared with normal bladder tissue." (PMID 34852826, 2021). "We found that both BAY 1816032 treatment and BUB1 knockdown resulted in the regression tumour growth, as demonstrated by decreased tumour volumes and weights of mice in the experiment group." (PMID 34337852, 2021). "It was shown that Bub1 promotes TGF-β signaling in mouse tumor tissues and that this is dependent on Bub1 kinase activity." (PMID 33717411, 2021). "A survival plot was generated to analyze the correlation between NMIBC progression and the combination index of tumor grade and BUB1 expression." (PMID 34884561, 2021). "Inhibition of BUB1 markedly suppressed cell proliferation and tumour growth, cell migration, invasion and induced cell apoptosis of OS by blocking the PI3K/Akt and ERK signalling pathways." (PMID 34337852, 2021). "shRNA silencing inhibits the expression of BUB1 gene in glioblastoma tumor cells, thereby reducing the proliferation and tumorigenicity of tumor cells in vivo and in vitro." (PMID 33767726, 2021). "BUB1 was also downregulated in the breast cancercells after ectopic expression of miR-302/367 cluster.BUB1 is a serine/threonine kinase playing a significantrole in cell cycle regulation, chromosome cohesion,and it is a key mediator of TGF-βsignaling." (PMID 31376326, 2020). "Inhibition of BUB1 can further prevent tumor proliferation and increase cell apoptosis by regulating TGF β / Smad signaling pathway." (PMID 33160391, 2020). "The results of the RT-qPCR demonstrated that mRNA expression of BUB1 was significantly higher in 14 of the tumor samples compared with the matched normal tissues." (PMID 32269624, 2020). "Immunohistochemistry analysis revealed that BUB1 was primarily expressed in the cytoplasm, and the tumor tissues exhibited increased staining intensity compared with the paired normal tissues in five patients, consistent with the results of RT-q PCR." (PMID 32269624, 2020).